PRDM1 (PR/SET domain 1)
Diseases named in the same sentence as PRDM1 in open-access papers (continued):
Sharing a sentence is not in itself a finding about the gene and the disease.
leukemia (13 papers, 2008 to 2025). A malignant (clonal) hematologic disorder, involving hematopoietic stem cells and characterized by the presence of primitive or atypical myeloid or lymphoid cells in the bone marrow and the blood. "Other genes like ZNF292, PRDM1, and CDH11 demonstrated promoter active demethylation and were previously linked to different leukemia types, where PRDM1 and CDH11 were reported to be frequently epigenetically silenced in these tumors." (PMID 41516186, 2025). "Fasting suppresses leukemia progression in part through increased leptin receptor expression, which leads to the activation of the PRDM1 gene encoding the BLIMP1 transcription factor." (PMID 37124486, 2023). "In mouse models, fasting induced leptin receptor activity was shown to promote B- and T-ALL differentiation and reduce leukaemia burden in a manner dependent on induction of PRDM1." (PMID 36670235, 2023). "Deletions of 6q involving FOXO3 and/or PRDM1 may therefore promote leukaemia survival partly by reducing sensitivity to leptin receptor signalling." (PMID 36670235, 2023). "PRDM1 knockout promoted TCF7-dependent CAR T cell stemness and proliferation, resulting in marginally enhanced leukemia control in mice." (PMID 36350986, 2022). "In the absence of PRDM1 agonists, dietary restriction or FOXO activation would feasibly elevate PRDM1 expression from the remaining allele to levels where leukaemia cells differentiate." (PMID 36670235, 2023). "In leukemia, a previous study reported that fasting could slow the progression of acute lymphoblastic leukemia (ALL) but not acute myeloid leukemia (AML) by activating the protein PR/SET domain 1 (PRDM1)-mediated leptin receptor and downstream signaling." (PMID 35246220, 2022).
glioma (12 papers, 2014 to 2024). A benign or malignant brain and spinal cord tumor that arises from glial cells (astrocytes, oligodendrocytes, ependymal cells). "Interestingly, diminished PRDM1 expression is linked to poor survival and aggravated pathological grade of human glioma and IL-33 is found to express heterogeneously in cancerous tissues and shares an association with inferior survival in patients suffered from relapse GBM." (PMID 35927251, 2022). "PRDM1 has been reported to affect the progression of glioma, and IL-33 has been demonstrated to promote the stemness of tumor stem cells." (PMID 35927251, 2022). "Of these, IRF1, IRF2, and PRDM1 were upregulated in all grades of glioma, while CEBPB was just upregulated in grade III and combined." (PMID 33948562, 2021). "We found that 4 of 26 predicted TFs (IRF1, IRF2, CEBPB, and PRDM1) were upregulated at the mRNA level in MR1 high gliomas." (PMID 33948562, 2021). "MiR-30a is involved in Wnt signaling pathway through the regulation of PRDM1 during glioma cell growth." (PMID 27734929, 2016). "DKK1 is a target gene of the Wnt pathway, and PRDM1 has recently been proposed to enhance DKK1 levels through an alternative mechanism in glioma cells." (PMID 24733089, 2014). "Indeed, PRDM1 expression levels decreased significantly with ascending glioma grade and correlated positively with Dickkopf-1 LDL low-density lipoprotein (DKK1) levels." (PMID 32290321, 2020). "Both SEPT7 and PRDM1 have been found to be targeted by miR-30a in gliomas." (PMID 26472042, 2015). "The expression levels of PDL1 (CD274), FOXO1, and PRDM1 in the high-HIF1A-expression group were significantly higher in both glioblastoma (GBM) and lower-grade glioma." (PMID 34305618, 2021). "Higher levels of PRDM1 were observed in high-HIF1A-expression GBM and lower-grade glioma, while higher levels of NFAT and IL10 were only observed in lower-grade glioma." (PMID 34305618, 2021).
influenza infection (12 papers, 2010 to 2025). "Nevertheless, we found higher expression of CD25, CD122, and phospho-STAT5 (pSTAT5) in all populations (TFH, TFR, cTreg, and TEFF cells) in the medLNs of influenza-infected Prdm1-CKO mice as compared to WT mice." (PMID 40680114, 2025). "We next sought to better understand the effects of Prdm1 deletion on IL-2–induced gene expression following influenza infection." (PMID 40680114, 2025). "Purified CD4+ T cells from medLNs of influenza-infected WT (Prdm1fl/fl) and Prdm1-CKO (Prdm1fl/flCD4cre) mice were treated with IL-2 for 24 hours after ex vivo influenza-specific peptide (NP311–325) stimulation and subjected to RNA sequencing (RNA-seq) analysis." (PMID 40680114, 2025).
malaria (12 papers, 2016 to 2023). Malaria is a serious and sometimes fatal disease caused by a parasite that commonly infects a certain type of mosquito which feeds on humans. "It demonstrated that IL21R was expressed in healthy individuals in malaria-endemic areas before the start of the malaria season and down-regulated a week after treatment of the first acute malaria episode (in convalescence), while TLR7, TLR9, PRDM1, and CD38 showed the opposite pattern." (PMID 36380692, 2022).
Crohn disease (11 papers, 2015 to 2024). A gastrointestinal disorder characterized by chronic inflammation involving all layers of the intestinal wall, noncaseating granulomas affecting the intestinal wall and regional lymph nodes, and transmural fibrosis. "SNPs in the region of PRDM1 have been associated with Crohn’s disease and inflammatory bowel disease." (PMID 38664626, 2024). "It has been reported that mutations in the positive regulatory domain 1 (PRDM1) locus, encoding B lymphocyte–induced maturation protein 1 (BLIMP1), are associated with Crohn’s disease (CD)." (PMID 35503415, 2022). "Reanalysis of published data sets also revealed an inverse correlation between PRDM1 and IL21 in Crohn’s disease." (PMID 35503415, 2022).
inflammatory bowel disease (11 papers, 2012 to 2025). A spectrum of small and large bowel inflammatory diseases of unknown etiology. "Genes over-expressed in human inflammatory bowel disease showed differential expression in LPLs from infected mice in the absence of Prdm1 or Maf, revealing potential mechanisms of human disease." (PMID 38609547, 2024).
COVID-19 (8 papers, 2022 to 2025). A disease caused by infection with severe acute respiratory syndrome coronavirus 2. "For example, PRDM1 (encoding BLIMP-1) in monocytes 40 and TCF family TFs (including TCF7) motifs in CD4 naive T cells are uniquely enriched in COVID-19 samples 40,41." (PMID 37425926, 2025). "The PRDM1- plasma cells are characterized by sub-optimal differentiation or activation, which may be defective or even inhibit productive antibody responses in COVID-19." (PMID 36119105, 2022). "The exhaustion/effector driving TFs (PRDM1, MAF) were also upregulated in COVID-19 patients that eventually succumbed to the disease." (PMID 36119105, 2022).
ulcerative colitis (8 papers, 2015 to 2025). An inflammatory bowel disease involving the mucosal surface of the large intestine and rectum. "Several polymorphisms in PRDM1 are risk alleles for ulcerative colitis, CD, SLE, and RA, although they have not been formally associated with impaired Tregs." (PMID 40773294, 2025).
diabetes (6 papers, 2020 to 2025). "Notably, PRDM1 and ZFPFM2 may serve as therapeutic targets for TC in patients with concurrent diabetes." (PMID 40965127, 2025).
seminoma (6 papers, 2008 to 2020). A radiosensitive malignant germ cell tumor found in the testis (especially undescended), and extragonadal sites (anterior mediastinum and pineal gland). "This suggests that in PRDM1/H4R3me2s positive TCam-2-ΔSOX2 cells, somatic differentiation is epigenetically blocked, contributing to maintenance of a seminoma-like cell fate." (PMID 27283990, 2016). "During in vitro differention of TCam-2 into a mixed non-seminoma and during the in vivo reprogramming, PRDM1 is downregulated and excluded from the nucleus." (PMID 27283990, 2016). "From them, EC-, pluripotency- and reprogramming-associated genes REX1 (ZFP42), DND1, JARID2 and PRDM14 were hypomethylated and upregulated, while seminoma-related genes PRDM1, PROM1 and IGF1 became hypermethylated and were downregulated." (PMID 26226633, 2015). "Furthermore, IHC demonstrated nuclear localization of PRDM1, which is a hallmark of GCNIS/seminomas, while in ECs PRDM1 is located in the cytoplasm." (PMID 27283990, 2016). "Additionally, global 5mC levels remained unaffected and expression of seminoma-associated genes SOX17, PRAME, TFAP2C, PRDM1 and cKIT was maintained." (PMID 27283990, 2016). "Additionally, the BMP /SMAD signaling is reduced, putatively leading to downregualtion of PRDM1, allowing for differentiation into a mixed non-seminoma." (PMID 26226633, 2015). "Expression of typical seminoma markers (PRDM1/BLIMP1, SOX17, PRAME, TFAP2C) was also detectable in TCam-2-ΔSOX2/FOXA2 tumor tissues, in contrast to EC reprogramming factors (GDF3, DPPA3, DNMT3B, GAL), which could only be detected in 2102EP in vivo or reprogrammed TCam-2 cells." (PMID 31130628, 2019). "TCam-2 cells express typical primordial germ cell and GCNIS marker genes (SOX17, PRAME, cKIT, TFAP2C, PRDM1/BLIMP1) and show a typical GCNIS/seminoma morphology (big roundish cells with a big nucleus and clear cytoplasm)." (PMID 31130628, 2019). "In TCam-2-ΔSOX2 clones, expression of seminoma markers SOX17, PRAME, TFAP2C, LIN28 and PRDM1 was slightly downregulated or remained unchanged compared to the TCam-2 in vitro cells." (PMID 27283990, 2016). "Most importantly, the majority of TCam-2-ΔSOX2 cells maintains a seminoma-like cell fate for at least 6 weeks in vivo, indicated by a typical seminoma-like morphology and expression of seminoma markers SOX17, PRAME, TFAP2C and PRDM1 (nuclear)." (PMID 27283990, 2016). "Analyses of these cells revealed downregulation of the pluripotency and seminoma markers OCT3/4, SOX17, PRDM1 and TFAP2C." (PMID 27283990, 2016). "Pluripotency and seminoma markers like NANOG, OCT3/4, LIN28, TFAP2C, cKIT, D2-40 and PRDM1 were downregulated." (PMID 27283990, 2016). "PRDM1, the transcription factor TFAP2C and SOX17 render the PGCs and seminomas in a state of dormant pluripotency, meaning that they express pluripotency markers, but are not able to induce differentiation into somatic tissues." (PMID 26226633, 2015). "In these somatic microenvironments, TCam-2 cells upregulate EC-markers SOX2, CD30, DNMT3B/L and downregulate seminoma markers SOX17, cKIT and PRDM1." (PMID 26226633, 2015). "Additionally, strong and comparable expression of the seminoma and pluripotency markers OCT3/4, NANOG, LIN28, SOX17, PRAME, PRDM1/BLIMP1 and TFAP2C was found in TCam-2, TCam-2-ΔSOX2 and TCam-2-ΔSOX2/FOXA2 cells." (PMID 31130628, 2019). "Additionally, many pluripotency and EC associated genes, like SOX2, ZIC3, ZFP42, LIN28, SALL4 and PRDM14 were upregulated without correlating to changes in their 5mC status, while seminoma markers SOX17, cKIT, PRDM1 and PRAME were downregulated." (PMID 27283990, 2016). "Nuclear PRDM1 and the H2A/H4R3me2s was also found in human seminomas, but not in ECs." (PMID 27283990, 2016).
seminoma (continued). "However, with downregulation of PGC- (PRDM1, TFAP2C, cKIT) and pluripotency (NANOG, OCT3/4, LIN28) marker genes, persisting SOX17 expression together with activation of the Hippo pathway resulted in differentiation into a mixed non-seminoma with predominant choriocarcinoma-like components." (PMID 26226633, 2015). "We stratified the TCGA dataset of 156 samples into a seminoma expression signature (SOX17, PRAME, PRDM1 positive; SOX2, DNMT3B, GAL negative) and an EC expression signature (SOX2, DNMT3B, GAL positive; SOX17, PRAME, PRDM1 negative)." (PMID 32418994, 2020). "Furthermore, TCam-2-ΔSOX2/FOXA2 derived tumors stained positive for pluripotency and seminoma markers OCT3/4, SOX17, TFAP2C, and PRDM1/BLIMP1, but were negative for the differentiation-markers AFP and EOMES." (PMID 31130628, 2019).
colorectal cancer (5 papers, 2020 to 2024). A primary or metastatic malignant neoplasm that affects the colon or rectum. "The expression of several zinc finger proteins, such as ZEB1, ZFX and PRDM1, has been reported to be associated with the survival of colorectal cancer patients." (PMID 33892786, 2021). "Kim and Moon find that the transcription factor PRDM1 is induced by ribosomal dysfunction in colorectal cancer (CRC) cells and associated with chemoresistance through a pathway involving IGF signaling." (PMID 33972671, 2021). "However, it has been highly controversial for the involvement of PRDM1 in regulation of solid tumors, including colorectal cancer (CRC)." (PMID 33972671, 2021).
parasitic infection (5 papers, 2016 to 2023). "From this, we identified 26 common DEGs downregulated in Tr1 cells from both parasitic diseases, including Ccr7, Tcf7, and Bcl6, as well as 29 upregulated DEGs, including Il10, Havcr2, Prdm1, Ccr2, Ccr5, Maf, and Lag3." (PMID 37917177, 2023).
acute lymphoblastic leukemia (4 papers, 2022 to 2023). Leukemia with an acute onset, characterized by the presence of lymphoblasts in the bone marrow and the peripheral blood. "Pan-HDAC inhibitors have been reported to elevate PRDM1 expression levels in follicular lymphoma cells, and we also found that another pan-HDAC inhibitor, PCI-24781, could elevate PRDM1 expression levels in T cell acute lymphoblastic leukemia (T-ALL) cells." (PMID 35572579, 2022).
atherosclerosis (4 papers, 2018 to 2025). A disease characterized by the build-up of fatty material and calcium deposition in the arterial wall resulting in partial or complete occlusion of the arterial lumen. "This study highlights a PRDM1-regulated T cell network that distinguishes high-risk from low-risk plaques and demonstrates the regulatory role of T cell PRDM1 in controlling atherosclerosis, positioning this pathway as a promising therapeutic target." (PMID 41039608, 2025). "In particular, a murine atherosclerosis model revealed that Prdm1 deficiency in T cells resulted in significant plaque growth and enhanced necrotic core formation, while reducing T cell numbers." (PMID 41039608, 2025). "In summary, this in vivo murine model strongly supports the protective role of T cell-specific PRDM1 in atherosclerosis, with Prdm1 deficiency leading to larger, more advanced plaques and a reduction in T cell populations." (PMID 41039608, 2025). "Since RUNX3 is reported to exert much of its T cell regulatory function through PRDM1, we focused on the role of T cell PRDM1 in atherosclerosis." (PMID 41039608, 2025). "Our study aligns with these findings, showing that the PRDM1-driven gene module plays a protective role in atherosclerosis." (PMID 41039608, 2025). "The association of PRDM1 with atherosclerosis was further underpinned by analysis of an independent human CEA plaque cohort (BiKE), showing almost ten fold higher expression of PRDM1 (P < 0.0001) in atherosclerotic (n = 127) than in control non-atherosclerotic artery tissue (n = 10)." (PMID 41039608, 2025). "Additionally, our mouse model does not fully represent late-stage symptomatic atherosclerosis, so the role of PRDM1 in advanced disease remains uncertain." (PMID 41039608, 2025).
hepatocellular carcinoma (4 papers, 2021 to 2025). A malignant tumor that arises from hepatocytes. "Positive regulatory domain containing 1 (PRDM1) functions as a double-edged sword in hepatocellular carcinoma (HCC) progression." (PMID 38715050, 2024). "Here the authors show that PRDM1/BLIMP1 promotes immune evasion by regulating PD-L1 expression in hepatocellular carcinoma cells." (PMID 36509766, 2022).
Sepsis (4 papers, 2020 to 2025). Sepsis is defined as life-threatening organ dysfunction caused by a dysregulated host response to infection. "Several upregulated genes may contribute to T cell exhaustion, including PRDM1 and CXCR4 (1.32 and 0.52log2FC, respectively), which have been implicated in a murine model of sepsis." (PMID 41208955, 2025).
bladder cancer (3 papers, 2021 to 2026). "From the perspective of the direct targeting of molecules, it has been demonstrated that the inhibition KPNA2 (e.g., via the PRDM1/c-FOS pathway) has antitumor effects in bladder cancer models." (PMID 41413918, 2025). "The role of PRDM1 in various tumors is controversial, and its specific mechanism in bladder cancer (BCa) remains unclear." (PMID 41724787, 2026).
cervical cancer (3 papers, 2017 to 2026). A primary or metastatic malignant neoplasm involving the cervix. "Subsequent siRNA-mediated knockdown in pCCa-1 cervical cancer cells targeting these factors revealed that only PRDM1 silencing substantially downregulated SLC30A9 mRNA expression." (PMID 41419464, 2025). "Functional experiments demonstrated a significant reduction in SLC30A9 expression at both the mRNA and protein levels following PRDM1 silencing or KO in primary cervical cancer cells." (PMID 41419464, 2025). "Concomitantly, PRDM1 depletion resulted in decreased luciferase activity driven by the SLC30A9 promoter in primary cervical cancer cells, further supporting the role of PRDM1 in regulating SLC30A9 transcription." (PMID 41419464, 2025). "Using the same viral shRNA and CRISPR/Cas9 techniques, we were able to successfully knock down and knock out PRDM1 in primary cultured pCCa-1 cervical cancer cells." (PMID 41419464, 2025). "Importantly, ChIP assays revealed significantly increased binding of PRDM1 to the SLC30A9 promoter region in cervical cancer tissues, providing strong evidence for PRDM1’s direct involvement in upregulating SLC30A9 expression." (PMID 41419464, 2025). "Furthermore, ChIP analysis in human tissues, using two distant primer pairs (Primer Pair #1 and Primer Pair #2), demonstrated that the binding activity of PRDM1 to the SLC30A9 promoter region was significantly elevated in cervical cancer tissues compared to adjacent normal cervical tissues." (PMID 41419464, 2025). "Silencing or knockout of PRDM1 resulted in a significant reduction in SLC30A9 promoter activity, as well as decreased SLC30A9 mRNA and protein levels in primary cervical cancer cells." (PMID 41419464, 2025). "PRDM1 silencing or KO led to a marked decrease in both SLC30A9 mRNA and protein expression levels in pCCa-1 primary cervical cancer cells, accompanied by a significant reduction in the luciferase activity of the SLC30A9’s promoter." (PMID 41419464, 2025). "In the Human Protein Atlas, OVOL1 and PRDM1 showed low, ENO1 medium, while ZNF365 showed no protein expression in cervical cancer." (PMID 28670312, 2017).